WT1 (WT1 transcription factor)
Diseases named in the same sentence as WT1 in open-access papers (continued):
Sharing a sentence is not in itself a finding about the gene and the disease.
serous carcinoma (40 papers, 2013 to 2026). "As regards immunohistochemistry in this diagnostic setting, WT1 immunoreactivity in a high-grade serous carcinoma, particularly if diffuse, favors tubo-ovarian origin (90%–95% of tubo-ovarian high-grade serous adenocarcinomas are WT1 positive)." (PMID 30550485, 2019). "WT1 positivity was significantly associated with advanced FIGO stages in serous carcinomas." (PMID 41930078, 2026). "Nuclear WT1 positivity was predominantly observed in serous carcinomas, while mucinous and seromucinous tumors were WT1-negative." (PMID 41930078, 2026). "Calretinin and WT-1, although sometimes positive in smooth muscle tumors, were also useful in excluding a mesothelial origin or serous carcinoma, particularly given the presence of ascites and adnexal adhesions." (PMID 41199837, 2025). "Care is needed to differentiate FTCS from high-grade serous carcinoma, which also shows WT1 positivity." (PMID 40933897, 2025). "WT-1 was a highly sensitive and specific IHC marker for diagnosing ovarian high-grade serous carcinomas." (PMID 36556009, 2022). "WT1 is regarded as a specific and sensitive indicator of serous carcinomas of ovarian origin, and studies have shown that the expression of WT1 in endometrial carcinoma is closely related to tumor hematopoiesis." (PMID 34975540, 2021). "It is worth noting that some studies reported rates of WT1 expression for endometrioid and serous carcinoma (n." (PMID 32859123, 2020). "The subgroup analysis of uterine cancer types revealed that WT1 was expressed differently among different histotypes (endometrioid, clear cell, serous carcinoma and carcinosarcoma)." (PMID 32859123, 2020). "Overall, WT1 expression showed association with OS and DFS/RFS/PFS in endometrioid carcinoma and with OS, especially for serous carcinoma and clear cell carcinoma patients." (PMID 32859123, 2020). "Several studies have shown that WT1 is expressed in more than 90% of high-grade serous carcinomas of the ovary and more rarely in serous carcinomas of the endometrium." (PMID 29621151, 2018). "The carcinomatous component is positive with pan-keratin (AE1/AE3), PAX8 and WT1 (serous carcinoma)." (PMID 29621151, 2018). "Pitfalls exist: PAX8 (MRQ50 clone) and WT1 may be positive in high-grade serous carcinomas but can occasionally stain TNBC, necessitating careful interpretation." (PMID 41301002, 2025). "WT1 negativity in the ovarian tumor excluded high-grade serous carcinoma." (PMID 36292027, 2022). "Additionally, we stained ER/PR and p16 for endometriod carcinoma, HNF1b for clear cell carcinoma, and WT1 for additive serous carcinoma, and performed a multiple rounding consensus triage." (PMID 35328131, 2022). "However, since endometrioid carcinomas are usually WT1-negative, diffuse WT1 expression when present suggests a diagnosis of serous carcinoma, including derivation from an adnexal serous carcinoma." (PMID 30550483, 2019). "Almost all of 64 high-grade serous carcinomas expressed WT1 in 75–100% of their nuclei." (PMID 30057405, 2018).
serous carcinoma (continued). "In addition, WT1 is the most important immunohistochemical marker to distinguish serous carcinoma from CCC." (PMID 27912770, 2016). "Therefore, the WT1-ve and ER -ve pattern in both tumors of this case indicated that serous carcinoma in the uterine myometrium was most likely primary from adenomyosis, which had largely been replaced by tumor overgrowth." (PMID 27260518, 2016). "WT1 expression is usually focally positive (in up to 30% of cases) or negative in uterine serous carcinoma 27, and this marker is therefore not routinely applied in the differential diagnosis between grade 3 endometrioid carcinoma and serous carcinoma at this anatomic site." (PMID 30550483, 2019). "Typical high-grade serous carcinoma is positive for Wilms' tumor 1 (WT-1), and therefore negative staining for WT-1 favors metastatic carcinoma." (PMID 30693167, 2018). "Positive WT1 staining was related with poorer survival in subtypes of the nonserous carcinomas, but not in the group of serous carcinomas." (PMID 24715586, 2014). "Negative WT1 immunoreactivity excluded the possibility of high-grade serous carcinoma." (PMID 36292027, 2022). "Moreover, the tumors exhibited diffuse expression of PAX8, WT1, and CK7, but no CK20 expression, suggesting that they were high-grade serous carcinomas with Müllerian origin." (PMID 29560094, 2018).
myelodysplastic syndrome (38 papers, 2007 to 2025). A clonal hematopoietic disorder characterized by dysplasia and ineffective hematopoiesis in one or more of the hematopoietic cell lines. "WT1 mutations have also been reported in 3–4% of myelodysplastic syndrome (MDS) and have been associated with an increased risk of transformation to AML." (PMID 30450160, 2018). "WT1 is a tumor-associated antigen that is expressed constantly in leukemic cells during acute leukemia and myelodysplastic syndrome (MDS)." (PMID 31852498, 2019). "Wilms’ Tumor Gene (WT1) is consistently expressed in myeloid leukemia cells, including those affected by myelodysplastic syndrome (MDS), AML, and chronic myeloid leukemia (CML)." (PMID 39411712, 2024). "Supporting this perspective, the upregulation of both HIF1α and WT1 has been reported in patients with myelodysplastic syndrome (MDS) or acute leukemia." (PMID 35465313, 2022). "A phase 1/2 study investigated the effect of DSP-7888, a novel WT1-based peptide vaccine, in patients with myelodysplastic syndrome (MDS)." (PMID 35280755, 2022). "No patients showed any new chromosomal abnormalities or an increase in the WT1 mRNA copy number of peripheral blood or progression to clonal disorders, including myelodysplastic syndromes and PNH." (PMID 35847715, 2020). "Similar WT1 mutations have been reported in adult patients with myelodysplastic syndrome (MDS)." (PMID 30450160, 2018). "Wild-type Wilms' tumor gene WT1 is expressed at a high level in hematopoietic malignancies including acute leukemia, chronic myelogenous leukemia, and myelodysplastic syndromes, as well as in various kinds of solid cancers." (PMID 17619750, 2007). "A notable example in current research is the development of Wilms’ Tumor 1 (WT1) peptide vaccines for treating myelodysplastic syndrome (MDS) patients." (PMID 40382583, 2025). "Our findings correlate with data in the literature when it was shown that WT1 is overexpressed in mRNR and protein levels in solid cancers, such as brain, breast, cervical, colon, glioblastoma, and others, and blood cancers, such as acute and chronic leukemia, myeloma, and myelodysplastic syndrome." (PMID 35495123, 2022). "WT1 is overexpressed in acute leukemias and myelodysplastic syndromes (MDS) and has limited expression on normal CD34+ hematopoietic stem cells." (PMID 34943884, 2021). "In another patient with AML, which likely evolved from a myelodysplastic syndrome (MDS), the MDS and secondary AML samples shared a mutation in IDH1 and the AML gained additional mutations only in NRAS and WT1 genes." (PMID 29312904, 2017). "Pre-transplant measurable residual disease status of WT1 ccf-mRNA expression has been assessed for prognostic value in peripheral blood obtained from patients with Acute Myeloid Leukemia and Myelodysplastic syndrome (MDS)." (PMID 37091783, 2023). "For example, Wilms tumour antigen 1 (WT1) is expressed in leukaemic cells including acute myeloid leukaemia (AML) and myelodysplastic syndromes (MDS), at much higher levels than in normal stem cells or other tissues." (PMID 24935654, 2014). "LAAs such as New York esophageal squamous cell carcinoma-1 (NYESO-1) in multiple myeloma or Wilms tumor antigen 1 (WT1)-TCR in AML and myelodysplastic syndrome (MDS) have been clinically investigated and can be employed both in a autologous and in a allogeneic setting." (PMID 31878060, 2019). "Previous studies have suggested that Wilms’ tumor gene-1 (WT1) may be related to a decrease in both relapse-free survival (RFS) and overall survival (OS) for patients with myelodysplastic syndrome (MDS)." (PMID 29662637, 2018).
Ewing sarcoma (36 papers, 2005 to 2025). A small round cell tumor that lacks morphologic, immunohistochemical, and electron microscopic evidence of neuroectodermal differentiation. "The hallmark of this disease is a EWS-WT1 translocation resulting from apposition of the Ewing’s sarcoma (EWS) gene with the Wilms’ tumor (WT1) gene." (PMID 23922674, 2013). "WT1 nuclear stain against the C terminus can be used to differentiate DSRCTs (WT1+) from Ewing sarcoma/primitive neuroectodermal tumors, neuroblastomas, or rhabdoid tumors of the kidney (WT1−)." (PMID 39682287, 2024). "Positivity for desmin and WT1 nuclear staining in addition to positive epithelial markers strongly favors a diagnosis of DSRCT over that of Ewing sarcoma and rhabdomyosarcoma." (PMID 31103034, 2019). "Previous work from our laboratory showed that WT1 is upregulated by hypoxia in the MHH-ES Ewing sarcoma cell line which expresses only low levels of WT1 under normoxic conditions." (PMID 25794157, 2015). "Similar to our published findings with Ewing sarcoma cells, hypoxia upregulates WT1 mRNA expression in U937 cells." (PMID 25794157, 2015). "Although these differences did not quite reach statistical significance (p=0.08), when viewed in the context of the results with MHHshRNA tumors, these results confirm that WT1 expression modulates in vivo tumor growth of Ewing sarcoma xenografts." (PMID 24810959, 2014). "One of the most striking differences between the vessels seen in Ewing sarcoma xenografts that express only a single WT1 isoform is their morphology." (PMID 24810959, 2014). "We also demonstrate that WT1 regulates the expression of a panel of pro-angiogenic molecules in Ewing sarcoma cell lines." (PMID 24810959, 2014). "In a Ewing sarcoma xenograft model, we found that tumors which express high levels of WT1 demonstrate increased angiogenesis, while suppression of WT1 dramatically diminishes angiogenesis." (PMID 24810959, 2014). "We expressed exogenous WT1 in the WT1-null Ewing sarcoma cell line, SK-ES-1, and we suppressed WT1 expression using shRNA in the WT1-positive Ewing sarcoma cell line, MHH-ES." (PMID 24810959, 2014). "We confirmed that WT1 expression positively regulates angiogenesis in Ewing sarcoma xenografts, and found that WT1 modulates VEGF isoform expression as well." (PMID 24810959, 2014). "Our immunohistochemistry studies demonstrate that WT1 expression modulates tumor angiogenesis in Ewing sarcoma xenografts." (PMID 24810959, 2014). "Our laboratory demonstrated that WT1 is upregulated by hypoxia in Ewing sarcoma cells in vitro, and that in these cells, WT1 is a direct positive regulator of vascular endothelial growth factor (VEGF) expression." (PMID 24810959, 2014). "Further research targeting the EWS/WT1 translocation (as currently being explored in early phase trials of the Ewing sarcoma) may provide promise in this difficult to treat disease." (PMID 29853779, 2018). "In the present study, we tested the hypothesis that WT1 is a key regulator of tumor angiogenesis in Ewing sarcoma." (PMID 24810959, 2014). "Having demonstrated that WT1 expression modulates angiogenesis in our Ewing sarcoma xenografts, we next investigated whether this translated into an effect on tumor growth." (PMID 24810959, 2014). "The work reported here strengthens the hypothesis that WT1 is an important regulator of tumor angiogenesis by demonstrating the direct correlation between WT1 expression and angiogenesis in Ewing sarcoma xenografts as well as in primary tumors." (PMID 24810959, 2014). "Finally, we found a tight correlation between WT1 expression and angiogenesis in primary Ewing sarcoma." (PMID 24810959, 2014). "Our work clearly shows that, in the context of Ewing sarcoma, WT1 is pro-angiogenic." (PMID 24810959, 2014). "Further support for this hypothesis comes from our angiogenesis array experiments, which demonstrate that suppression of WT1 in Ewing sarcoma cells reduces expression of a significant number of pro-angiogenic genes." (PMID 24810959, 2014).
Ewing sarcoma (continued). "The majority (16 out of 21, 76.2%) of the Ewing sarcoma samples stained for WT1 protein." (PMID 24810959, 2014). "To investigate whether VEGF and MMP9 expression in primary Ewing sarcoma correlate with WT1 expression, we performed immunohistochemical analysis of 21 paraffin-embedded Ewing sarcoma samples." (PMID 24810959, 2014). "Thus, in these Ewing sarcoma xenografts, modulating WT1 expression has a significant effect on the extent of tumor vasculature, and in conditions that alter the relative expression of isoforms, vascular morphology is also affected." (PMID 24810959, 2014). "Taken together, these findings support the hypothesis that WT1 is a key mediator of tumor angiogenesis in Ewing sarcoma." (PMID 24810959, 2014). "Based on our observation that WT1 can upregulate VEGF in Ewing sarcoma cell lines, we tested the hypothesis that WT1 regulates tumor angiogenesis in Ewing sarcoma xenografts and in primary Ewing sarcoma tumors." (PMID 24810959, 2014). "Cytogenetical studies have demonstrated a reciprocal chromosome translocation between the Ewing's sarcoma gene on chromosome 22 and the Wilms' tumour gene WT1 on chromosome 11, which is distinct from the translocation observed in Ewing sarcoma/peripheral neuroectodermal tumor (PNET)." (PMID 15777480, 2005). "Regardless of the value arbitrarily set to assign significance, taken together, our findings with MHH-ES and SK-ES-1 cells support the hypothesis that WT1 is a pro-angiogenic factor in Ewing sarcoma, and this pro-angiogenic effect results in increased tumor growth." (PMID 24810959, 2014). "The rearrangement of the RNA-binding protein EWSR1 characterizes a variety of malignant tumors, including Ewing’s sarcoma (EWSR1/ETS), depilated small round cell tumor (EWSR1/WT1), and some acute lymphoblastic leukemia (EWSR1/ZNF384)." (PMID 35686089, 2022). "Presence of translocation t(11:22) (p13:q12), which results in active fusion of Ewing sarcoma (EWS) and Wilms tumor (WT1) genes, confirms the diagnosis of DSRCT." (PMID 34635162, 2021). "Our work implicates WT1 as a global regulator of Ewing sarcoma angiogenesis, and future work will clarify how NPY, REST, and WT1 interact." (PMID 24810959, 2014). "C19, an antibody to the C-terminal region of the WT1 protein, has been proven useful for differentiating DSRCT from Ewing sarcoma/primitive neuroectodermal tumor (EWS/PNET) when genetic information is unavailable." (PMID 25037705, 2014). "About 3/4 of Ewing sarcoma and DSRCT tumors have an identical EWS breakpoint motif at Exon 7 (SQQSSSYGQQ-) fused to a specific part of FLI1 (NPSYDSVRRG or-SSLLAYNTSS), ERG (NLPYEPPRRS), FEV (NPVGDGLFKD) or WT1 (SEKPYQCDFK)." (PMID 36900411, 2023). "Finally, WT1 expression was correlated with VEGF expression, MMP9 expression, and microvessel density (as reflected by CD31 expression) in samples of primary Ewing sarcoma." (PMID 24810959, 2014). "Finally, we found that WT1 expression is correlated with VEGF expression, MMP9 expression, and microvessel density in samples of primary Ewing sarcoma." (PMID 24810959, 2014). "Because our WT1-expressing xenografts showed more MMP9 expression by immunohistochemistry, we were interested in whether MMP9 is also a direct WT1 target gene in Ewing sarcoma cells." (PMID 24810959, 2014). "Interestingly, none of the Ewing’s sarcoma/primitive neuroectodermal tumors (0 of 21), neuroblastomas (0 of 17), or rhabdoid tumors of the kidney (0 of 2) were positive for WT1." (PMID 39682287, 2024). "The concept of WT1 as a global regulator of angiogenesis is further supported by our demonstration MMP9 is a direct target of the transcriptional regulatory activity of WT1 and identification of a small panel of additional pro-angiogenic molecules upregulated by WT1 in Ewing sarcoma cell lines." (PMID 24810959, 2014). "Ewing sarcomas/PNETs show CD99-positive staining in the cytoplasm and not in the cell membrane and are negative for CK, EMA, WT1, and desmin." (PMID 34193155, 2021).
Ewing sarcoma (continued). "As in Ewing sarcoma, the chimerical protein included the EWSR1 N-terminal domain and the SP3 zinc finger DNA-binding domain but not the inhibitory domain of SP3-domain of WT1." (PMID 22587803, 2012).